ARHGAP5 (Rho GTPase activating protein 5)
Diseases named in the same sentence as ARHGAP5 in open-access papers (continued):
Sharing a sentence is not in itself a finding about the gene and the disease.
tumor (continued). "Although previous studies suggested that ARHGAP5 may play an oncogenic role in tumor progression, its biological function and regulatory mechanisms in CRC are poorly understood." (PMID 32483433, 2020). "Recently, ARHGAP5 was identified as an oncogene that promotes tumor metastasis." (PMID 30250020, 2018). "Additionally, the down-regulation of miR-486-5p was reportedly responsible for both tumor progression and metastasis by relieving the inhibition of protumorigenic ARHGAP5 in lung cancer." (PMID 26370615, 2015). "Moreover, hsa_circ_0003258 may upregulate the expression of Rho GTPase activating protein 5 (ARHGAP5) to promote tumor progression by sponging miR-653-5p." (PMID 34986849, 2022). "Furthermore, multivariate Cox regression analysis further confirmed the depth of tumor infiltration (T stage, p = 0.013), local lymph node metastasis (N stage, p = 0.008), and ARHGAP5 levels (p = 0.001) as independent predictors of the overall survival of GC patients." (PMID 30250020, 2018). "Previous study has reported that ARHGAP5 could promote tumor cells proliferation." (PMID 25961434, 2015). "T24 cells transfected with scramble shRNA (sh-NC) and shRNA targeting ARHGAP5, ARHGAP17, and ARHGAP24 were injected into nude mice subcutaneously, and knockdown of these genes significantly reduced BC tumor growth." (PMID 34307347, 2021). "In particular, our analysis highlighted ARHGAP5 and ARFGEF1 as previously unreported putative driver genes of tumor progression in this cancer type." (PMID 32732999, 2020). "PCR analysis also confirmed that ARHGAP5 was significantly upregulated in CRC liver metastatic tissues and primary tumor tissues compared to matched adjacent-normal tissues." (PMID 32483433, 2020). "SIRT1 restraints the progression of GC via the modulation of ARHGAP5 expression, representing a novel mechanism of SIRT1 as a tumor suppressor." (PMID 31130822, 2019). "The frequency of subcutaneous tumor development in NSG mice was significantly increased in organoids carrying gRNAs targeting Arhgap5 or Mecom compared with that in the non-target gRNA control, showing that the two genes are tumor suppressors." (PMID 37845228, 2023). "Moreover, the IHC results of tumor tissues also showed that sh-hsa_circ_0003258 had lower expression of HDAC4 and ARHGAP5 in the lungs compared with the vector." (PMID 34986849, 2022). "As a sponge of miR-516b-5p, circUBE2K could up-regulate expression of target gene ARHGAP5, and thus promote EMT and exert tumor stimulating effect on proliferation and metastasis." (PMID 34285193, 2021). "It should be noted that we did not examine the possibility that ADAR1 may impact ARHGAP5 mRNA or protein to affect tumor progression in this study, which will also be explored in the future." (PMID 36077054, 2022).
cancer (26 papers, 2008 to 2025). A tumor composed of atypical neoplastic, often pleomorphic cells that invade other tissues. "Although previous studies suggested that ARHGAP5 was associated with tumors, its underlying regulatory mechanisms in cancer cells are controversial and poorly understood." (PMID 32483433, 2020). "So far, no study has identified mutations in the p190B-encoding gene ARHGAP5 in cancers." (PMID 31013840, 2019). "We further found that METTL3 and ARHGAP5 mRNA and protein levels were significantly decreased in ADAR1-loss cancer tissues compared to the Ctrl sgRNA group." (PMID 36077054, 2022). "Canonical CTNNB1 p.Ser45Pro missense mutation, as well as several other cancer-related genes (e.g., PML, HSP90AA1, BAZ1A, ARHGAP5, LHFPL6), were detected in the PT sample." (PMID 35860547, 2022). "In agreement with our data, ARHGAP5 was shown to induce metastatic dissemination in different cancers." (PMID 36307394, 2022). "For the data set of OV, 67 genes were identified by univariate Cox regression to be significantly associated with the cancer and seven of them, namely COL1A1, COL3A1, RPL10, ARHGAP5, LATS1, TSHR and SLC34A2, were found in the CGC data set." (PMID 32429941, 2020). "miR-486 has been shown to participant in general tumorigenesis by targeting the anti-apoptotic OLFM4, SIRT1, PIM-1 and protumorigenic ARHGAP5 in various types of cancer." (PMID 27167342, 2016). "Reduced expression of miR-486–5p increases ARHGAP5 expression and enhances migration and invasion of cancer cells." (PMID 26417931, 2015). "Interestingly, instead of decreasing the expression of ARHGAP5, it was shown that miR-744 bound directly to the promoter and increased the expression of ARHGAP5 to drive these processes of cancer progression." (PMID 32353968, 2020). "Given the prognostic value of ARHGAP5 and its correlation with metastasis in CRC, we next sought to determine whether ARHGAP5 contributes to metastasis by affecting cancer cell migration and/or proliferation, which are 2 critical determinants of metastasis." (PMID 32483433, 2020). "This suggests a more complex regulatory mechanism of miRNAs with ARHGAP5 in cancer." (PMID 32353968, 2020). "Second, in our previous study, we were unable to separate the function of p190A from that of p190B encoded by the ARHGAP5 gene, which is not significantly mutated in human cancer." (PMID 32641858, 2020). "Moreover, emerging evidence shows that ARHGAP5 is upregulated in cancers and contributes to invasive and metastatic behavior." (PMID 30250020, 2018). "ARHGAP5 expression was also detected in all the myometrial biopsies examined, with a difference in size, with the HeLa protein band being shifted down the gel, possibly due to alternative posttranslational modifications or a truncated ARHGAP5 version in the cancer cell line." (PMID 18190708, 2008). "Immunohistochemical staining showed that CXCR4, RhoA, RhoGEF, ARHGAP5, PI3K, ROCK, PAK and PKN were significantly up-regulated in cancer tissues compared with normal tissues." (PMID 27517626, 2016). "HeLa cell lysate was also used in the other western blots, with expression of ARHGEF1, ARHGEF11, ARHGEF12, ARHGAP5, ARHGAP24 and ARHGDIA protein reported in this cancer cell line." (PMID 18190708, 2008). "ARHGAP5 can also promote cancer progression regardless of the activation state of RhoA." (PMID 38783033, 2024).
infection (3 papers, 2012 to 2020). The state of being infected such as from the introduction of a foreign agent such as serum, vaccine, antigenic substance or organism. "Then, we stably knocked down ARHGAP5 by the lentiviral infection of shRNA targeting ARHGAP5 in SW620 and HCT15 cells which expressed higher level of ARHGAP5." (PMID 32483433, 2020). "We verified the PPARs pathway-mediated generation of ANGPTL4 in BMECs in response to meningitic E. coli challenge and demonstrated for the first time that ANGPTL4-triggered ARHGAP5/RhoA/MYL5 signaling cascade contributed to the BBB disruption by the infection." (PMID 31766605, 2019). "We demonstrated preliminarily that meningitic E. coli induced the expression of ANGPTL4 through the activation of PPARβ/δ signaling pathway, and ANGPTL4 contributed to the infection-mediated BBB disruption via the ARHGAP5/RhoA/MYL5 signaling cascade, affecting the actin cytoskeleton." (PMID 31766605, 2019). "As shown, the ARHGAP5 exhibited a significantly decreased expression in hBMECs along with the infection, while in contrast, the RhoA exhibited an increasing expression in response to the infection, which is exactly consistent with the concept that ARHGAP5 could negatively regulate RhoA." (PMID 31766605, 2019).
ARHGAP5 also shares sentences with these, for which no sentence is quoted: adenocarcinoma (2 papers); Anorexia (1); bacterial meningitis (1); colorectal adenoma (1); Hearing impairment (1); lung (1); meningitis (1); metastatic colorectal cancer (1); renal agenesis (1).